CCDC181 (coiled-coil domain containing 181)
Description:
Microtubule-binding protein that is essential for the integrity and function of the manchette, facilitating proper sperm head shaping and subsequent flagellum formation during spermatogenesis.
Synonyms: C1orf114; FLJ25846
Tractability: No criterion of Open Targets' tractability assessment is met for any kind of drug.
Gene: Protein-coding gene on chromosome 1 (169,394,870 to 169,460,669, reverse strand). Ensembl gene ENSG00000117477.
Subcellular location: Cytoplasm, cytoskeleton; Cell projection, cilium, flagellum; Cell projection, cilium; Cytoplasm, cytoskeleton, cilium axoneme
Subcellular location (Human Protein Atlas): Acrosome; Mid piece; Nuclear speckles; Principal piece
Gene Ontology:
Molecular function: microtubule binding
Biological process: manchette assembly; sperm flagellum assembly; spermatid development
Cellular component: axoneme; cilium; manchette; sperm flagellum; cytoskeleton; motile cilium
Genetic constraint (gnomAD): Loss-of-function variants: 30 observed, 47.86 expected, observed/expected ratio (o/e) 0.63, 90% interval 0.47 to 0.85. The upper end of that interval is the gene's LOEUF score, 0.85, which puts it in group 3 of 6, group 1 being the genes least tolerant of losing a copy. Missense variants: 469 observed, 550.14 expected, observed/expected ratio (o/e) 0.85, 90% interval 0.79 to 0.92. Synonymous variants: 164 observed, 189.22 expected, observed/expected ratio (o/e) 0.87, 90% interval 0.76 to 0.99.
Homologues: Orthologues: chimpanzee CCDC181 (99% identical), macaque CCDC181 (95% identical), dog CCDC181 (85% identical), pig CCDC181 (84% identical), guinea pig CCDC181 (78% identical), mouse Ccdc181 (75% identical), rabbit CCDC181 (75% identical), rat Ccdc181 (75% identical), zebrafish ccdc181 (35% identical).
Diseases named in the same sentence as CCDC181 in open-access papers:
CCDC181 is named in the same sentence as 19 diseases in open-access papers, as found by Europe PMC text mining. Sharing a sentence is not in itself a finding about the gene and the disease. The quoted sentences say what the papers report.
prostate carcinoma (8 papers, 2017 to 2024). A carcinoma that arises from epithelial cells of the prostate gland. "Although aberrant methylation of CCDC181 was found in lung and prostate cancer in previous studies and in endometrial cancer in Taiwanese cohort, aberrant methylation of CCDC181 was a good cancer biomarker with high sensitivity (81.5%) in breast cancer." (PMID 33803633, 2021). "Furthermore, CCDC181 methylation has been suggested to be a prognostic biomarker in prostate cancer and lung cancer." (PMID 35328380, 2022). "Aberrant methylation of CCDC181 has been reported in patients with lung and prostate cancer." (PMID 33803633, 2021). "ctDNA analysis based on methylation of three of these genes (ST6GALNAC3, CCDC181, and HAPLN3) could detect prostate cancer with 100% diagnostic specificity and 67% diagnostic sensitivity." (PMID 33942482, 2021). "In the same study, using ddPCR, promoter methylation of these two genes (ST6GALNAC3 and ZNF660) and additionally CCDC181 and HAPLN3 was evaluated in ctDNA of 27 patients with prostate cancer and 10 patients with benign prostate hyperplasia using MS‐ddPCR." (PMID 33942482, 2021). "In this study, we show that prostate cancer-specific hypermethylation of the eight genes AOX1, CCDC181 (C1orf114), GABRE, GAS6, HAPLN3, KLF8, MOB3B, and SLC18A2 can be detected by qMSP with very high sensitivity and specificity in scarce prostate needle biopsy samples taken at the time of diagnosis." (PMID 28084441, 2017).
breast carcinoma (3 papers, 2021 to 2023). "Especially in BrCa, CCDC181 methylation was suggested as a biomarker with which to estimate the breast cancer cell fraction in tissue samples, corroborating our results." (PMID 35328380, 2022). "CCDC181 methylation was also found in breast cancer biopsy specimens purified by laser capture microdissection, and it was selected as a fraction marker." (PMID 33803633, 2021). "Most breast cancer-specific circulating methylated CCDC181, GCM2 and ITPRIPL1 biomarkers were found in the plasma." (PMID 33803633, 2021). "The breast cancer specificity of methylated CCDC181, GCM2, ITPRIPL1, LOC643719 and ZNF177 ranged from 64.3 to 100%, indicating lower false-positive signals." (PMID 33803633, 2021). "In this study, we carry out automatic detection of circulating cell-free methylated DNA, including GCM2, ITPRIPL1 and CCDC181, and find a pattern that can detect early breast cancer more accurately compared with currently used biomarkers." (PMID 33803633, 2021). "The data indicated that the aberrant circulating hypermethylated CCDC181, GCM2 and ITPRIPL1 detected in the plasma samples were also significantly present in the associated tumor tissues of breast cancer patients (Spearman’s rho = 0.702, 0.497 and 0.634, all p < 0.001)." (PMID 33803633, 2021). "To further determine the methylation pattern of breast cancer tissues in the Taiwanese cohort, we analyzed the methylation levels of CCDC181, GCM2, ITPRIPL1, ENPP2, LOC643719, ZNF177 and ADCY4 in tumors and adjacent normal tissue in Taiwanese breast cancer patients." (PMID 33803633, 2021). "Combined analysis of CCDC181, GCM2 and ITPRIPL1 was performed by Recursive Partitioning and Regression Trees (RPART) using 57 breast cancer and 134 health plasma samples from the subjects." (PMID 33803633, 2021). "Aberrant methylation patterns of the CCDC181, GCM2 and ITPRIPL1 genes are highly prevalent in Western and Taiwanese breast cancer patients, suggesting that they are potential biomarkers for early prediction in Western and Asian countries." (PMID 33803633, 2021). "As promising biomarkers, circulating methylated CCDC181, GCM2 and ITPRIPL1 are expected to improve the detection of breast cancer." (PMID 33803633, 2021). "Aberrant methylation of CCDC181, GCM2, ITPRIPL1, ENPP2, LOC643719, ZNF177 and ADCY4 was found in breast cancer patients from the Taiwanese and TCGA cohorts using the methylation array." (PMID 33803633, 2021). "Circulating methylated CCDC181, GCM2 and ITPRIPL1 was detected in 57.1–84.6% of ductal carcinoma in situ (DCIS) tumors from breast cancer patients." (PMID 33803633, 2021). "The heatmap revealed hypermethylation of CCDC181, GCM2 and ITPRIPL1 in tumors of breast cancer patients compared with adjacent normal tissues from the Taiwanese and TCGA cohort (respectively)." (PMID 33803633, 2021). "Hypermethylation of CCDC181, GCM2 and ITPRIPL1 was found in more than 80% of patients with lower tumor histologic grades, and in 70% of early-stage breast cancer among all subtypes of breast cancer patients." (PMID 33803633, 2021). "Hypermethylation of CCDC181, GCM2 and ITPRIPL1 was observed in different subgroups of breast cancer patients, including in individuals of different races and in various menopause states as well as with different tumor stages and histological types." (PMID 33803633, 2021). "The methylation patterns of the CCDC181, GCM2, ITPRIPL1, ENPP2, LOC643719, ZNF177 and ADCY4 genes were further determined in plasma samples from healthy and early breast cancer patients." (PMID 33803633, 2021). "Aberrant methylation patterns of the CCDC181, GCM2, ITPRIPL1, ENPP2, LOC643719, ZNF177 and ADCY4 genes were identified and further evaluated in paired tumor and normal tissues of breast cancer patients." (PMID 33803633, 2021).
breast carcinoma (continued). "The box plot demonstrates an increase in CCDC181, GCM2 and ITPRIPL1 in tumors of Taiwanese breast cancer patients compared with the adjacent normal tissues using the paired-sample Wilcoxon test (Z score −9.02, −7.94, −8.65, p < 0.001)." (PMID 33803633, 2021). "Few studies have reported the clinical significance and application of aberrant CCDC181, GCM2 and ITPRIPL1 methylation in breast cancer." (PMID 33803633, 2021). "Therefore, the profiles of CCDC181, GCM2 and ITPRIPL1 in breast cancer were selected for further analysis." (PMID 33803633, 2021). "The results for seven candidate genes—CCDC181, GCM2, ITPRIPL1, ENPP2, LOC643719, ZNF177 and ADCY4—were successfully validated by sequencing and stable detection in ccfDNA from the plasma of Taiwanese patients with breast cancer." (PMID 33803633, 2021). "Circulating methylated CCDC181, GCM2 and ITPRIPL1 analysis could be combined with ultrasound to facilitate the early detection of breast cancer." (PMID 33803633, 2021). "Hypermethylation of CCDC181 and GCM2 could be detected in ductal carcinoma in situ (DCIS) tumors of breast cancer patients." (PMID 33803633, 2021). "Finally, the most breast cancer-specific biomarkers, circulating methylated CCDC181, GCM2 and ITPRIPL1 (CGIm), were identified in patients with early-stage breast cancer." (PMID 33803633, 2021). "The aberrant methylation patterns of the CCDC181, GCM2 and ITPRIPL1 genes means that they are potential biomarkers for the detection of early BC and can be combined with breast imaging data to achieve higher accuracy, sensitivity and specificity, facilitating breast cancer detection." (PMID 33803633, 2021). "Therefore, we suggested that the methylation pattern of circulating CCDC181, GCM2 and ITPRIPL1 could be combined with mammography or/and ultrasonography and applied for the early prediction of breast cancer." (PMID 33803633, 2021). "To further investigate whether the use of circulating methylated CCDC181, GCM2 and ITPRIPL1 biomarkers could improve the detection of breast cancers, we combined the ultrasonography BI-RADS (3 and 4a) and circulating methylated CCDC181, GCM2 and ITPRIPL1 levels." (PMID 33803633, 2021).
breast tumors (1 paper, 2021). "The data suggested that methylated circulating CCDC181, GCM2 and ITPRIPL1 were mostly derived from primary tumors and could serve as new postsurgical monitoring biomarkers for the detection of residual tumors, with the exception of primary breast tumors." (PMID 33803633, 2021).
endometrial cancer (1 paper, 2021). Primary or metastatic malignant neoplasm involving the endometrium (mucous membrane that lines the endometrial cavity). "In our Taiwanese cohort, hypermethylation of CCDC181 in tumors was also found in 66.7% of endometrial cancer samples compared with adjacent normal tissues." (PMID 33803633, 2021).
tumor (7 papers, 2018 to 2024). "Therefore, aberrant methylation of CCDC181, which is prevalent in female cancer, could serve as a general female tumor marker." (PMID 33803633, 2021). "Correlation analysis showed that the methylation of the PRDM14, CACNA1E, CCDC181, and GCM2 genes correlated with tumor size." (PMID 37628841, 2023). "The level of methylation in four genes—PRDM14, CACNA1E, CCDC181, and GCM2—correlated with tumor size." (PMID 37628841, 2023). "According to initial in silico biomarker analyses, CCDC181 DNA methylation differences were only observable in PCa tumour tissues compared to healthy prostate tissue but not within blood-derived cfDNA." (PMID 38611002, 2024). "To further determine the origin of circulating methylated CCDC181, GCM2 and ITPRIPL1, we analyzed whether the DNA methylation between plasma and matched tumor tissues showed a similar pattern." (PMID 33803633, 2021). "Moreover, as proof of principle, we successfully detected highly PC‐specific hypermethylated circulating tumor DNA (ctDNA) for ST6GALNAC3,ZNF660,HAPLN3, and CCDC181 in liquid biopsies (serum) from 27 patients with PC vs. 10 patients with BPH, using droplet digital methylation‐specific PCR analysis." (PMID 29465788, 2018).
cancer (4 papers, 2017 to 2021). A tumor composed of atypical neoplastic, often pleomorphic cells that invade other tissues. "Because T. annulata-transformed host cells have cancer hallmarks, we propose that CCDC181 might be used as a biomarker for tropical theileriosis in future studies." (PMID 34116718, 2021).
CCDC181 also shares sentences with these, for which no sentence is quoted: lung carcinoma (3 papers); hepatocellular carcinoma (2); bladder cancer (1); colorectal cancer (1); ductal carcinoma in situ (1); esophageal squamous cell carcinoma (1); esophagus cancer (1); Fibroadenoma (1); gastric cancer (1); liver cancer (1); ovarian carcinoma (1); pancreatic cancer (1); uterine cancer (1).